CXXC4 (CXXC finger protein 4)
Diseases named in the same sentence as CXXC4 in open-access papers (continued):
Sharing a sentence is not in itself a finding about the gene and the disease.
tumor (14 papers, 2017 to 2024). "Decreased expression of negative regulators of Wnt signaling, including SFRP1, DKK-3, and CXXC4, is correlated with increased cytoplasmic β-catenin levels and tumor progression." (PMID 34657130, 2021). "The Dishevelled (Dvl) inhibitor Idax, coded by the CXXC4 gene, seems to be involved in tumour cell invasiveness and proliferation, and its expression is associated with poor prognosis." (PMID 33959797, 2021). "CXXC4 is a negative regulator of Wnt/β-catenin signaling in RCC, and the CXXC4 mRNA level gradually decreases in RCC as the tumor stage and grade increases." (PMID 34657130, 2021). "In this research, the functions of CXXC4 in regulating the fate of tumour cells and differentiation at the T cell level were intriguing." (PMID 32715641, 2020). "Note that none of the patients with high CXXC4 expression (n = 46) had tumor recurrence, while eight of the patients with low CXXC4 expression (n = 56) presented with recurrence after surgery." (PMID 33230461, 2020). "Meanwhile, CXXC4 expression in tumor tissues was determined by western blot analysis, the results of which revealed significantly downregulated CXXC4 expression in the presence of EV-miR-675-3p mimic (p < 0.05)." (PMID 33230461, 2020). "The tumor suppressor functions of CXXC4 are also well-characterized and CXXC4 inhibits Wnt/β-catenin signaling through its interaction with Disheveled 25-27." (PMID 33033513, 2020). "The results from our study were further indicative of the presence of poor expression of CXXC4 in GC and that high expression of CXXC4 led to a low tumor recurrence rate." (PMID 33230461, 2020). "Collectively, CXXC4 is a tumour suppressor that controls the growth of tumour cells and the statuses of T cells which will further target the tumour cells and kill them." (PMID 32715641, 2020). "CXXC4 is a tumour suppressor expressed at low levels in tumours compared to normal tissues." (PMID 32715641, 2020). "As a tumor repressor, the regulation of CXXC4 expression in transcription level has been reported." (PMID 30042169, 2018). "Previously, CXXC4 was identified as a tumor suppressor regulated by EZH2." (PMID 29262584, 2017). "We show that DPT functions as a tumor suppressor in HCC and inhibits Wnt signaling through CXXC4 mediated β-catenin degradation." (PMID 33033513, 2020). "Down-regulated expression was observed for the tumor suppressor and inhibitor of WNT signaling CXXC4, and the differentiation inducing transcription factors, HOXA7 and HOXA9." (PMID 29100312, 2017). "CXXC4 and TET2 at 4q24 were equally potential targets for tumor suppression." (PMID 35677048, 2022). "Furthermore, CXXC4, being capable of inhibiting the mitogen-activated protein kinases (MAPK) signalling pathway, is emerging as a novel tumour suppressor." (PMID 33959797, 2021).
cancer (9 papers, 2016 to 2024). A tumor composed of atypical neoplastic, often pleomorphic cells that invade other tissues. "CXXC4 levels, along with KPNA4 and SMC4, have been associated with cancer progression." (PMID 34187551, 2021). "As a transcription factor, CXXC4 functions via multiple targets in various cancer types." (PMID 30042169, 2018). "The candidate gene CXXC finger protein 4 (CXXC4), was also annotated in this region and is involved in inhibiting cancer cell growth by regulating the Wnt/β-catenin pathway." (PMID 39327557, 2024).
CXXC4 also shares sentences with these, for which no sentence is quoted: breast carcinoma (1 paper); colorectal adenocarcinoma (1); dilated cardiomyopathy (1); mucoepidermoid carcinoma (1); neurodevelopmental disorder (1); neutropenia (1).